SENP3 (SUMO specific peptidase 3)
Description:
Protease that releases SUMO2 and SUMO3 monomers from sumoylated substrates, but has only weak activity against SUMO1 conjugates. Deconjugates SUMO2 from MEF2D, which increases its transcriptional activation capability. Deconjugates SUMO2 and SUMO3 from CDCA8. Redox sensor that, when redistributed into nucleoplasm, can act as an effector to enhance HIF1A transcriptional activity by desumoylating EP300. Required for rRNA processing through deconjugation of SUMO2 and SUMO3 from nucleophosmin, NPM1. Plays a role in the regulation of sumoylation status of ZNF148. Functions as a component of the Five Friends of Methylated CHTOP (5FMC) complex; the 5FMC complex is recruited to ZNF148 by methylated CHTOP, leading to desumoylation of ZNF148 and subsequent transactivation of ZNF148 target genes. Deconjugates SUMO2 from KAT5. Catalyzes desumoylation of MRE11.
Synonyms: SSP3; DKFZP586K0919; DKFZp762A152; SMT3IP1; Ulp1
Tractability: PROTAC: ubiquitination databases record sites on it; its protein half-life has been measured.
Target class: Enzyme; Hydrolase
Gene: Protein-coding gene on chromosome 17 (7,561,919 to 7,571,969, forward strand). Ensembl gene ENSG00000161956.
Subcellular location: Nucleus, nucleolus; Nucleus, nucleoplasm; Cytoplasm
Subcellular location (Human Protein Atlas): Nucleoli; Nucleoplasm
Pathways (Reactome):
Metabolism of RNA: Major pathway of rRNA processing in the nucleolus and cytosol
Gene Ontology:
Molecular function: cysteine-type peptidase activity; deSUMOylase activity; protein binding; cysteine-type deubiquitinase activity
Biological process: negative regulation of double-strand break repair via homologous recombination; protein desumoylation; cleavage in ITS2 between 5.8S rRNA and LSU-rRNA of tricistronic rRNA transcript (SSU-rRNA, 5.8S rRNA, LSU-rRNA); proteolysis
Cellular component: MLL1 complex; nucleolus; nucleoplasm; nucleus; rixosome complex; cytoplasm
Genetic constraint (gnomAD): Loss-of-function variants: 10 observed, 60.16 expected, observed/expected ratio (o/e) 0.17, 90% interval 0.1 to 0.28. The upper end of that interval is the gene's LOEUF score, 0.28, which puts it in group 1 of 6, group 1 being the genes least tolerant of losing a copy. Missense variants: 544 observed, 725.86 expected, observed/expected ratio (o/e) 0.75, 90% interval 0.7 to 0.8. Synonymous variants: 286 observed, 272.9 expected, observed/expected ratio (o/e) 1.05, 90% interval 0.95 to 1.16.
Homologues: Orthologues: chimpanzee SENP3 (99% identical), macaque SENP3 (99% identical), pig SENP3 (97% identical), guinea pig SENP3 (97% identical), rabbit SENP3 (97% identical), dog SENP3 (96% identical), rat Senp3 (95% identical), mouse Senp3 (94% identical), zebrafish senp3a (45% identical), zebrafish senp3b (44% identical), tropical clawed frog senp3 (32% identical), zebrafish senp5 (23% identical), and 3 more. Paralogues in human: SENP5 (33% identical), SENP1 (20% identical), SENP2 (20% identical).
Diseases named in the same sentence as SENP3 in open-access papers:
SENP3 is named in the same sentence as 69 diseases in open-access papers, as found by Europe PMC text mining. Sharing a sentence is not in itself a finding about the gene and the disease. The quoted sentences say what the papers report.
gastric cancer (7 papers, 2014 to 2022). A primary or metastatic malignant neoplasm involving the stomach. "SENP3 was confirmed to be related to gastric cancer metastasis in vivo models and tumor patient specimens." (PMID 36698419, 2022). "The correlation between SENP3 and gastric cancer metastasis was proven by the nude mouse model and patient specimens." (PMID 33192553, 2020). "Sp1 (specificity protein 1) is a cancer-associated transcription factor, and the level of Sp1 was significantly increased in parallel to the SENP3 level in gastric cancer cell lines, nude mice, and specimens derived from gastric cancer patients." (PMID 33192553, 2020). "The SENP3 level is increased in gastric cancer cells, and SENP3 deSUMOylates FOXC2, potentiates its transcriptional activity, induces the epithelial cell to interstitial cell changes, and promotes tumor invasion and metastasis." (PMID 33192553, 2020). "Taken together, the evidence shows that the expression level of SENP3 is increased in gastric cancer, and the increase in SENP3 increases deSUMOylation and enhances the tumorigenic activity of target proteins." (PMID 33192553, 2020). "In the present study, we have shown that H2O2 treatment leads to an increase of Sp1 in the gastric cancer cell line, which is dependent on an induction of SENP3." (PMID 26511642, 2016). "We herein show a close correlation between the protein levels of SENP3 and Sp1 in the patient’s gastric specimens, as well as in the nude mouse xenografts of human gastric cancers." (PMID 26511642, 2016). "In gastric cancer cell lines and specimens derived from patients and nude mice, the level of Sp1 was generally increased in parallel to the level of SENP3." (PMID 26511642, 2016). "We demonstrate that the expression of mesenchymal marker genes and cell migration ability are enhanced in SENP3-overexpressing gastric cancer cells and attenuated in SENP3-knockdown cells." (PMID 25216525, 2014). "A nude mouse model and a set of patient's specimens suggest the correlation between SENP3 and gastric cancer metastasis." (PMID 25216525, 2014). "The present study uncovers a novel role of SENP3 in promoting the EMT process in gastric cancer via regulating an EMT-inducing transcription factor, forkhead box C2 (FOXC2)." (PMID 25216525, 2014). "Next we assessed the levels of SENP3 protein in 60 gastric cancer tissue samples; 39 with lymph node metastasis and 21 without, and the cancer-adjacent normal tissues derived from the latter 21 specimens." (PMID 25216525, 2014). "Our work also reveals an increase of the SENP3 protein in gastric carcinoma and other types of human cancers." (PMID 25216525, 2014). "The primary gastric carcinoma samples with metastasis of peri-gastric lymph nodes (LN) (GC + LN(+)) bore further stronger SENP3 staining, compared with the GC + LN(-) samples." (PMID 25216525, 2014). "High expression of SENP3 enhanced cell migration in gastric cancer cells." (PMID 36698419, 2022). "However, SENP3 has been found to be highly expressed in malignant tumors, such as head and neck cancer, ovarian cancer, and gastric cancer." (PMID 36227136, 2022). "In addition, the study found that mesenchymal marker gene expression and cell migration were enhanced in gastric cancer cells highly expressing SENP3." (PMID 33192553, 2020). "SENP3 promotes EMT in gastric cancer cells by regulating the EMT inducer FOXC2." (PMID 33192553, 2020). "Finally, the correlation between SENP3 and Sp1 levels was evaluated in the xenografts of human gastric cancers grown in the nude mice." (PMID 26511642, 2016). "SGC7901 gastric cancer cells that had moderate SENP3 level were stably transfected with SENP3." (PMID 26511642, 2016). "Finally, but above all, the role of SENP3 in the metastasis of gastric cancers is strongly supported by the human gastric cancer specimens and the mouse models of metastasis." (PMID 25216525, 2014). "Importantly, de-conjugation of SUMO2/3 from FOXC2 by SENP3 exists endogenously in gastric cancer cells." (PMID 25216525, 2014).
gastric cancer (continued). "To validate whether SENP3 could induce the EMT in gastric cancer, we established two stable cell lines in which SENP3 was over-expressed in one with low basal SENP3 (SGC7901-SENP3) or knocked-down in one with high basal SENP3 (MGC803-sh-SENP3)." (PMID 25216525, 2014). "Taken togher, these data suggest that SENP3, which is induced by ROS in gastric cancer cells, may mediate the ROS-induced EMT process." (PMID 25216525, 2014). "We next explored whether the expression levels of SENP3 correlated with the expression of Sp1 in human gastric carcinoma specimens using immunohistochemistry performed on the continuous sections of 21 surgically dissected tissues derived from gastric cancer patients." (PMID 26511642, 2016). "Correlation between SENP3 expression and gastric cancer (GC) metastasis has also been reported." (PMID 35887358, 2022). "Screening several human gastric cancer cell lines, we found that the MKN45 and MGC803 lines exhibit marked differences in their SENP3 levels, and also had differences in their Sp1 levels (left)." (PMID 26511642, 2016). "We detected ROS level of the two gastric cancer cell lines, and found that MGC803, which had a higher level of SENP3, also had a higher level of ROS, in contrast to SGC7901." (PMID 25216525, 2014). "Immunohistochemical-positive staining for SENP3 was nearly negative in epithelial cells in the normal tissues of peri-gastric cancers (peri-GC), but was readily visible in epithelium of most of the gastric carcinoma tissues." (PMID 25216525, 2014). "In an attempt to determine whether SENP3 contributes to the EMT and gastric cancer metastasis, we performed the present study." (PMID 25216525, 2014). "In conclusion, SENP3, which is increased in gastric cancer cells, potentiates the transcriptional activity of FOXC2 through de-SUMOylation, in favor of the induction of specific mesenchymal gene expression in gastric cancer metastasis." (PMID 25216525, 2014). "For example, SENP3 deSUMOylates the HIF1α coactivator P300 to increase angiogenesis under hypoxia, deSUMOylates promyelocytic leukemia in response to mild oxidative stress, and de-SUMOylating FOXC2 to facilitate epithelial-mesenchymal transition in gastric cancer cells." (PMID 30640896, 2019).
breast carcinoma (6 papers, 2022 to 2025). "Another study illustrated that SENP3 deficiency induced M2 polarization via Akt Akt1 deSUMOylation in breast cancer." (PMID 41266856, 2025). "The mechanism underlying SENP3 downregulation and localization or translocalization upon M2 induction in breast cancer mouse models and patients warrants investigation in the future." (PMID 33932085, 2022). "Altogether, loss of SENP3 contributed to tumor progression and worse prognosis in patients with breast cancer." (PMID 33932085, 2022). "In breast cancer, high levels of SENP3 are linked to high levels of E2F targets, high tumor grade and poor prognosis." (PMID 35887358, 2022). "In addition, we have highlighted the SENP3 gene, involved in protein sumoylation, whose elevated levels have been linked to poor survival in breast cancer patients." (PMID 37367050, 2023). "Notably, Sentrin/SUMO‐specific protease 3 (SENP3) loss in macrophages accelerated breast cancer malignancy in ex vivo and in vivo models." (PMID 33932085, 2022). "Furthermore, SENP3 abundance in stroma was negatively associated with macrophage mass in breast cancer biopsies, and SENP3 level in macrophage determined the extent of M2 polarization, eventually associated with lymphatic metastasis." (PMID 33932085, 2022). "Thus, increased Akt1 SUMOylation as a result of SENP3 deficiency modulates polarization of macrophages to the M2 subtype within a breast cancer microenvironment, which in turn promotes tumor progression." (PMID 33932085, 2022). "Similarly, SENP3 loss associates with tumor progression in breast cancer." (PMID 35887358, 2022). "SENP3 depletion leads to increased AKT1 sumoylation in the breast cancer microenvironment, promoting macrophage polarization to the M2 subtype, which stimulates tumor growth and lymphatic metastasis." (PMID 35887358, 2022). "In human breast cancer tissues, lower SENP3 levels in macrophages were found to be significantly correlated with higher levels of the M2 marker mannose receptor, C type 1 (CD206) and, most importantly, with advanced malignancy, especially lymphatic metastasis." (PMID 33932085, 2022). "In mice, the deletion of SENP3 in macrophages promotes breast cancer progression and metastasis, according to recently published studies." (PMID 36698419, 2022). "This supports the conclusion that SENP3 downregulation in macrophage potentially accelerates the malignant progression of breast cancer." (PMID 33932085, 2022). "We utilized Py8119 cells derived from MMTV‐PyMT transgenic mice to generate allografts in Senp3 cKO mice via orthotopic, subcutaneous or tail vein injection, which mimicked rapid progression of breast cancer." (PMID 33932085, 2022). "The bioluminescence and histologic analyses showed increased lung colonization of the injected breast cancer cells in Senp3 cKO mice compared with WT mice." (PMID 33932085, 2022). "In this study, we reported that SENP3 deletion in macrophages elicited more M2 polarization and promoted tumor cell proliferation and metastasis within a breast cancer mouse model." (PMID 33932085, 2022). "Given that macrophage‐specific SENP3 deletion promoted breast cancer progression in mice, we examined the level of SENP3 in macrophages in human breast cancer tissues." (PMID 33932085, 2022). "Herein we discovered that the activity and polarization of TAM regulated by SENP3 facilitates tumor progression in the murine breast cancer model with Py8119." (PMID 33932085, 2022). "In summary, our study showed that SENP3 plays an important role in fine‐tuning macrophage polarization towards M2 in breast cancer via de‐SUMOylating Akt1." (PMID 33932085, 2022). "Kaplan–Meier analysis showed that a high SENP3 level in breast cancer tissues was correlated with a better overall survival." (PMID 33932085, 2022). "Next, Py8119 breast cancer cells were orthotopically injected into Senp3fl/fl mice (referred to as Senp3 WT hereafter) and Senp3 cKO mice, respectively." (PMID 33932085, 2022).
breast carcinoma (continued). "In the present study, we uncovered a previous unnoted role of SENP3 in fine‐tuning macrophage polarization in breast cancer." (PMID 33932085, 2022). "In addition, we measured SENP3 expression in other subtypes of breast cancer based on TCGA and GEO datebases." (PMID 36698419, 2022). "However, in HER2 and Lumina subtypes of breast cancer, SENP3 expresssion was decreased compared with normal tissues." (PMID 36698419, 2022). "SENP3, as a regulator of macrophage polarization, might serve as a potential therapeutic target and biomarker for lymphatic metastasis of breast cancer." (PMID 33932085, 2022). "Furthermore, in breast cancer patients, the decrease in SENP3 in macrophages is significantly correlated with M2 polarization, lymphatic metastasis or a worse prognosis." (PMID 33932085, 2022). "We then examined the correlation of SENP3 and CD206 among different intrinsic or molecular subtypes of breast cancer." (PMID 33932085, 2022). "The correlation of SENP3 in macrophages and CD206 in different subtypes of breast cancer patients." (PMID 33932085, 2022). "According to the data from Jordan NV (No. cells = 70), SENP3 might regulate DNA repair, DNA damage, the cell cycle and proliferation in breast cancer cells." (PMID 36698419, 2022). "In addition, the TIMER analysis of breast cancer patient data revealed a weak negative correlation between the SENP3 level in the whole tumor tissues and the number of macrophages that infiltrated the tumors." (PMID 33932085, 2022). "Furthermore, in breast cancer biopsies, SENP3 deficiency shows a strong negative correlation with expression of M2 markers in a variety of breast cancer subtypes, including TNBC, suggesting that SENP3 can be effective in suppressing M2 polarization." (PMID 35887358, 2022). "The lack of SENP3 can lead to an increase of AKT1 SUMOylation, thereby regulating the polarization of macrophages towards the M2 subtype, promoting the progression of breast cancer." (PMID 39314848, 2024).
hepatocellular carcinoma (6 papers, 2020 to 2026). A malignant tumor that arises from hepatocytes. "In this way, METTL16 plays a critical regulatory role in ferroptosis in hepatocellular carcinoma by modulating the expression and function of SENP3 and LTF." (PMID 41459114, 2026). ",108, 109 In hepatocellular carcinoma, METTL16 enhances the expression of SENP3 mRNA by catalyzing its m6A modification." (PMID 41459114, 2026). "CAFs promote hepatocellular carcinoma malignancy by SERPINH1 secretion and regulating SENP3-mediated SP1/SQLE pathway." (PMID 40959099, 2025). "In their study, SENP1 was stably expressed in hepatoma cells, while the expression level of SENP3 decreased, suggesting the possibility of negative feedback regulation of SENP3, which was consistent with the hypothesis in the present study." (PMID 36840491, 2023).
ischemia (5 papers, 2015 to 2021). A hypoperfusion of the BLOOD through an organ or tissue caused by a PATHOLOGIC CONSTRICTION or obstruction of its BLOOD VESSELS, or an absence of BLOOD CIRCULATION. "Our data suggest a protective role for SENP3 in whole heart, because preconditioning prior to ischemia reduced the extent of SENP3 loss from the cytosol compared to ischemia alone." (PMID 30973885, 2019). "We observed a 50% loss of SENP3 from the cytosolic fraction of hearts after preconditioning, a 90% loss after ischemia and an 80% loss after ischemia-reperfusion." (PMID 30973885, 2019). "Moreover, during ischemia, the decrease in cytosolic SENP3 is paralleled by an increase in nuclear SENP3, suggesting that ischemia could cause the relocation of SENP3 from the cytosol to the nucleus." (PMID 30973885, 2019). "Taken together, our results indicate that SENP3-mediated deSUMOlyation promotes an Mff-primed Drp1-Bcl-xL interaction that contributes to cell death following ischemia." (PMID 34722538, 2021). "Correlating with these data, we observed an increase in SENP3 in the nuclear fraction in the ischemia group, the condition in which there was the biggest decrease in cytosolic SENP3." (PMID 30973885, 2019). "Together, our data demonstrate that in whole perfused hearts short-term ischemia leads to a robust drop of cytosolic SENP3, while preconditioning attenuates this decrease." (PMID 30973885, 2019). "To directly address this controversy and characterise the molecular events that occur during ischemia and reperfusion, we investigated how SUMOylation and levels of SENP3 are altered by ischemia and ischemia-reperfusion in whole heart." (PMID 30973885, 2019). "In the cytosolic compartment, however, SENP3 levels were significantly decreased in the preconditioned, ischemia, and I/R groups." (PMID 30973885, 2019). "Here we provide a novel mechanistic explanation of how SENP3 promotes cell death during reperfusion after ischemia." (PMID 28262828, 2017). "Similarly, SENP3 expression levels varied greatly in different studies during ischemia and reperfusion with increased or unchanged levels following ischemia and reperfusion." (PMID 34869605, 2021). "Similar to whole hearts, ischemia induced a decrease in cytosolic SENP3." (PMID 30973885, 2019). "During ischemia, SENP3 levels decrease, promoting Drp1 SUMOylation." (PMID 28262828, 2017). "The SUMO-2/3-specific protease SENP3 is also found to be degraded during ischaemia, via a pathway involving the unfolded protein response (UPR) kinase PERK and the lysosomal enzyme cathepsin B. Ischaemia-induced cell death is suppressed as depletion of SENP3 prolongs Drp1 SUMOylation." (PMID 25987420, 2015). "Drp1 is a target for SUMOylation and its deSUMOylation, mediated by the SUMO protease SENP3, enhances the Drp1-Mff interaction to promote cell death in an oxygen/glucose deprivation (OGD) model of ischemia." (PMID 34722538, 2021).
colon carcinoma (4 papers, 2014 to 2022). "Like SENP1, SENP3 accumulates in several human cancers, with colon carcinomas having the highest ratio of SENP3 expression." (PMID 25315341, 2014). "Parallel studies confirmed that SENP3 ablation in Treg cells significantly suppressed tumor growth and enhanced antitumor immunity in the MC38 colon carcinoma model." (PMID 30089837, 2018).